BTG2 (BTG anti-proliferation factor 2)
Diseases named in the same sentence as BTG2 in open-access papers (continued):
Sharing a sentence is not in itself a finding about the gene and the disease.
bladder cancer (continued). "BTG2 expression was lower in human bladder cancer tissues than normal bladder tissues." (PMID 29239139, 2018). "Although widely deemed as a tumor suppressor gene, the role of BTG2 in human bladder cancer has not disclosed fully with higher BTG2 expression associated with reported poor prognosis of human bladder cancer patients." (PMID 29239139, 2018). "However, the exact role of BTG2 in bladder cancer is still inconclusive." (PMID 29239139, 2018). "Therefore, it is suggested further study to clarify the BTG2 role in bladder cancer." (PMID 29239139, 2018). "Expressions of BTG2 and PTEN in bladder carcinoma cells were determined by immunoblotting, RT‐qPCR, or reporter assays." (PMID 29239139, 2018). "The higher differentiated human bladder cancer cells, RT4, possessed higher BTG2 protein expression than other two less differentiated human bladder cancer cells, HT1376 and T24." (PMID 29239139, 2018). "Highly differentiated bladder cancer cells, RT4, expressed higher BTG2 than the less‐differentiated bladder cancer cells, HT1376 and T24." (PMID 29239139, 2018). "As compared to the highly differentiated bladder cancer cells, RT4, with other two less differentiated bladder cancer cells, HT1376 and T24, RT4 cells has higher BTG2 expression than HT1376 and T24 cells as determined by immunoblotting (top) and RT‐qPCR (bottom) assays." (PMID 29239139, 2018). "Since early study indicated that PTEN and BTG2 were canonical downregulated by miR‐21 overexpression in myeloma cells, we further demonstrated that PTEN also stimulated BTG2 in human bladder cancer." (PMID 29239139, 2018).
colorectal cancer (10 papers, 2017 to 2025). A primary or metastatic malignant neoplasm that affects the colon or rectum. "In nasopharyngeal carcinoma, miR-1278 exerts tumor-suppressive effects by targeting ATG28; miR-1278 expression is downregulated in colorectal carcinoma and tumor cell metastasis is inhibited by the targeting of CYP24A1, BTG2, and other downstream target genes." (PMID 38025524, 2023). "TOB2, BTG2 and BTG4 had no expression difference between colorectal cancer and normal tissues." (PMID 28922388, 2017).
medulloblastoma (9 papers, 2012 to 2026). A malignant, invasive embryonal neoplasm arising from the cerebellum. "Therefore, Btg2 could be implicated as a deregulated gene in the onset of the human medulloblastoma." (PMID 34395258, 2021). "However, BTG2 has been shown to largely suppress medulloblastoma by promoting the migration of cerebellar precursor cells out of the proliferative neuroepithelium." (PMID 26694352, 2015). "Additionally, BTG2 inhibits medulloblastoma, a very aggressive tumor of the cerebellum, by inhibiting proliferation and triggering the differentiation of the precursors of cerebellar granule neurons." (PMID 26694352, 2015).
non-small cell lung carcinoma (9 papers, 2018 to 2024). A group of at least three distinct histological types of lung cancer, including non-small cell squamous cell carcinoma, adenocarcinoma, and large cell carcinoma. "Up-regulated BTG2 could facilitate the apoptosis in non-small cell lung cancer and strengthen the effect of radio-sensitivity." (PMID 38062199, 2023). "In non-small cell lung cancer, BTG2 is a promising target for increasing radiation sensitivity with increased apoptosis and may be an early prognostic gene." (PMID 36765032, 2023). "Increased levels of LINC01504 in the non-small cell lung cancers cell lines A549, NCI-H1650, SK-MES-1 and NCI-H226 exposed to cinnamaldehyde promoted the production of cytokine signaling 1 (SOCS1), BTG anti-proliferation factor 2 (BTG2), and Bruton tyrosine kinase (BTK)." (PMID 36499073, 2022).
lymphoma (7 papers, 2014 to 2024). A malignant (clonal) proliferation of B- lymphocytes or T- lymphocytes which involves the lymph nodes, bone marrow and/or extranodal sites. "In this regard, it is of interest that also in this disorder the clonally expanded rogue B-cells harbor mutations of lymphoma-related genes (CARD11, TNFAIP3, CCND3, ID3, BTG2, KLHL6)." (PMID 39055707, 2024). "Some of these genes (such as the BTG2 gene, MYD88 gene and IL-25 genes) have been found to be closely related to the progression, chemotherapy resistance and inferior OS of lymphoma, and some have become potential therapeutic targets." (PMID 36221115, 2022). "Genomic profiling of B‐cell leukemia and lymphoma has put BTG1 and BTG2 in the spotlight, since both genes are frequently deleted or mutated in these malignancies, pointing towards a role as tumor suppressors." (PMID 30350856, 2019).
lung adenocarcinoma (6 papers, 2017 to 2024). A carcinoma that arises from the lung and is characterized by the presence of malignant glandular epithelial cells. "KIAA1429 knockdown significantly up-regulated BTG2 expression, whereas KIAA1429 overexpression slightly down-regulated BTG2 levels in lung adenocarcinoma." (PMID 39456252, 2024). "BTG2 and SerpinB5 were studied as a gene pair in our article to investigate their prognostic value in lung adenocarcinoma." (PMID 37006240, 2023). "For example, high expression of P4HB as well as low expression of BTG2 and CIT was associated with poor overall survival of lung adenocarcinoma patients (p-value of log-rank test < 0.05)." (PMID 36138770, 2022). "In a group of datasets including Beer, Selamat, Su, Hou and Wachi, BTG2 was downregulated in both lung adenocarcinoma and squamous cell lung carcinoma." (PMID 28922388, 2017). "The tumor suppressor protein B-cell translocation gene 2 (BTG2) is downexpressed in lung adenocarcinoma (LUAD); however, its role in LUAD survival remains unknown." (PMID 36157236, 2022). "Vectors expressing BTG2 were stably transduced into lung adenocarcinoma A549 cells." (PMID 36157236, 2022). "The results of Western blotting showed that BTG2, TLR2, and IL7R proteins were markedly downregulated in lung adenocarcinoma cell line A549, while CCL20 protein was markedly upregulated." (PMID 35372503, 2022).
diabetes (5 papers, 2020 to 2024). "Taken together, these findings suggest that the hepatic CRBN, CREBH, and BTG2 genes are upregulated during fasting and in patients with diabetes." (PMID 37488285, 2023). "The expression of the hepatic cereblon (CRBN) and b-cell translocation gene 2 (BTG2) genes was significantly increased in fasting mice, diabetic mice, and patients with diabetes." (PMID 37488285, 2023). "Notably, Btg2 mRNA is induced in the brain response to hypoxia–ischemia and in the brains of AD model mice with obesity-linked diabetes but not in those of AD model mice or mice with obesity-linked diabetes." (PMID 33812385, 2021). "BTG2 is thus speculated to be the target gene of lncRNA ENST00000432511 and may be involved in the pathogenesis of diabetes via the RNA degradation signal pathways." (PMID 32148491, 2020).
liver cancer (5 papers, 2018 to 2025). An epithelial or non-epithelial malignant neoplasm that arises from the liver. "The increased level of cyclin D1/cyclin E in liver cancer leading to the decreased BTG2 expression causes the increase of tumor grade." (PMID 34217312, 2021). "Kaplan–Meier curves indicate that liver cancer patients with high BTG2 expression have significantly longer survival time than those with low BTG2 expression." (PMID 34217312, 2021). "In addition, BTG2 expression in liver cancer cells was obviously declined and upregulation of BTG2 expression suppressed the proliferation and invasion while enhanced the apoptosis of HepG2 cells." (PMID 34217312, 2021).
periodontitis (5 papers, 2022 to 2026). An acute or chronic inflammatory process that affects the tissues that surround and support the teeth. "While the present study elucidated the expression pattern of miR-125a-5p in chronic periodontitis and its interaction mechanism with BTG2, several limitations should be acknowledged." (PMID 41542727, 2026). "BTG2 expression is markedly dysregulated in the periodontal tissues of patients with chronic periodontitis." (PMID 41542727, 2026). "BTG2 protects podocytes in DKD by linking autophagy regulation with inflammation pathways shared with periodontitis." (PMID 41009556, 2025). "In the present study, the significant upregulation of BTG2 in periodontitis patients suggests its potential involvement in the pathological process as a stress-responsive molecule." (PMID 41459503, 2025). "We will conduct further explorations in the future to examine the essential role of BTG2 and detailed pathway BTG2 located between periodontitis and DKD." (PMID 38831322, 2024). "Importantly, the miR-125a-5p/BTG2 regulatory pathway provides a novel target and approach for the development of molecularly targeted therapies for chronic periodontitis." (PMID 41542727, 2026). "In conclusion, the present study demonstrates that miR-125a-5p is markedly overexpressed in chronic periodontitis and promotes the degradation of periodontal tissues by enhancing oxidative stress and inflammatory responses in PDLFs through targeted inhibition of BTG2." (PMID 41542727, 2026). "Collectively, the miR-125a-5p/BTG2 pathway may serve as a key regulatory mechanism in the pathogenesis of chronic periodontitis, providing a promising molecular target for the development of innovative therapeutic strategies." (PMID 41542727, 2026). "Based on previous research, we hypothesize that altered BTG2 expression may indirectly influence the inflammatory state and osteoclastogenesis in periodontitis through modulation of the mTORC1 pathway." (PMID 41459503, 2025). "We not only identified a novel set of ISR-related biomarkers—BTG2, DERL3, FOS, HSPA13, and YOD1—but also revealed their potential associations with periodontitis-specific pathological features, such as osteoclast differentiation and the RANKL/OPG signaling pathway." (PMID 41459503, 2025). "The results showed that the gene BTG2 was a common DEG of periodontitis and DKD." (PMID 38831322, 2024). "Among the 13 periodontitis biomarkers, BTG2 and NSG1 were identified for the first time." (PMID 36457739, 2022). "Notably, the expression level of BTG2 in the periodontal tissues of patients with chronic periodontitis is significantly altered, suggesting that BTG2 may be involved in the inflammatory signalling network to regulate the destruction of periodontal tissues." (PMID 41542727, 2026). "In this study, BTG2, DERL3, FOS, and HSPA13 were significantly upregulated, and YOD1 was significantly downregulated in the gingival tissues of periodontitis patients, confirming their detectable presence locally." (PMID 41459503, 2025). "Analysis of GEO database data revealed BTG2 as a commonly differentially expressed gene in both DKD and periodontitis." (PMID 38831322, 2024). "BTG2 and NSG1 play an important role in apoptosis, and apoptosis is clearly involved in periodontitis and can serve as a biomarker." (PMID 36457739, 2022). "In conclusion, our study used both bioinformatic analysis and cellular functional assays to testify that BTG2 emerges as a key gene in the interaction between DKD and periodontitis, potentially up-regulating autophagy by inhibiting the mTORC1 signaling pathway, thereby inhibiting EMT." (PMID 38831322, 2024). "Our findings suggest that BTG2 is a crucial intermediary gene linking DKD and periodontitis." (PMID 38831322, 2024).
renal carcinoma (5 papers, 2018 to 2023). A carcinoma arising from the epithelium of the renal parenchyma or the renal pelvis. "An in vitro experiment had illustrated the inhibitory effect of raised BTG2 on the development of human renal carcinoma cells." (PMID 38062199, 2023). "Besides, over-expressed BTG2 also restricts cell migration and invasion in human renal carcinoma cell lines." (PMID 34699325, 2021).
cardiac hypertrophy (4 papers, 2016 to 2025). "In contrast, Btg2 is an immediate early gene induced by growth factors, and its function has been linked to cell cycle regulation or cardiac hypertrophy, a less likely candidate for transition factor in MCM." (PMID 40184463, 2025). "Interestingly, we identified four genes, Btg2, Egr1, Fos, and Atf3, associated with cardiac hypertrophy, in overlapping DEGs between the upregulated DEGs in PAH versus control groups and the downregulated DEGs in PAH/αKO versus PAH groups." (PMID 36736425, 2023). "Our single cell quantitative imaging analysis of cardiomyocytes found that Btg2 negatively regulates cardiac hypertrophy, opposing pro-hypertrophic stimuli by modulating cytosolic RNA levels." (PMID 27346836, 2016). "Among them, those coding for DUSP family members, CDKN1A, BTG2, GADD45B,34, and MCL-1 have been previously shown to be upregulated in human myocardial tissues in response to stress and/or DNA damage and to play a role in the regulation of cardiac hypertrophy and remodeling in animal models." (PMID 31924244, 2020). "To determine whether Btg2 is functionally relevant to the pathological hypertrophic response in cardiomyocytes, we prepared pressure-overloaded murine ventricular heart tissues by transverse aortic constriction (TAC) that induced significant cardiac hypertrophy." (PMID 27346836, 2016).
diabetic kidney disease (4 papers, 2023 to 2026). Progressive kidney disorder caused by vascular damage to the glomerular capillaries, in patients with diabetes mellitus. "Aberrant expression of BTG2 has been associated with multiple disorders, including tumorigenesis and diabetic nephropathy." (PMID 41542727, 2026). "First, we still lack the knowledge on Btg2 expression pattern in non‐FSGS podocyte diseases like diabetic nephropathy." (PMID 37749872, 2023). "In fact, we speculate that Btg2 may be highly expressed and play a role in promoting disease in diabetic nephropathy, membranous nephropathy, and minimal change disease manifested by podocyte injury, which needs to be further confirmed." (PMID 37749872, 2023).
melanoma (4 papers, 2015 to 2023). A malignant, usually aggressive tumor composed of atypical, neoplastic melanocytes. "When we assessed the association of TLR4, ITGA6, and BTG2 gene expression with melanoma prognosis, we observed that their higher expression (median cutoff) was significantly associated with a worse overall survival in TCGA SKCM cohort of 458 samples." (PMID 33980826, 2021). "From MetaCore network analysis, three hub genes (TLR4, ITGA6, and BTG2) were identified as targeted by multiple miRNAs, either up- or downregulated in multiple melanomas." (PMID 33980826, 2021). "Knockdown of miR-21 in B16 melanoma cells increases BTG2 levels, indicating that BTG2 is a miR-21 target in melanoma cells." (PMID 26116372, 2015). "In this study, we found six mitochondria-related genes, BTG2, CP, LRIG1, CYP1A1, GBP2, and MBNL1, which might be targets of quercetin in melanoma and play crucial roles in melanoma." (PMID 37869567, 2023). "Knockdown of miR‐21‐5p in melanoma cell lines reduces cell proliferation and migration, and promotes apoptosis by increasing the expression of programmed cell death 4 (PDCD4), phosphate and tensin homolog (PTEN) and BTG family member 2 (BTG2)." (PMID 30499222, 2019). "Combining the results of RNA-seq, molecular docking, and bioinformatics analysis, we found six mitochondria-related genes, BTG2, CP, LRIG1, CYP1A1, GBP2, and MBNL1, which might be targets of quercetin in melanoma and provide an available targeting therapy strategy for melanoma." (PMID 37869567, 2023).
Obesity (4 papers, 2021 to 2025). Accumulation of substantial excess body fat. "Research has shown that Btg2 expression is elevated in the subcutaneous adipose tissue of obese mice on a high-fat diet, highlighting its involvement in lipid metabolism during obesity and metabolic disorders." (PMID 41221287, 2025). "Other research has revealed that BTG2 was expressed in obesity." (PMID 34248836, 2021).
osteosarcoma (4 papers, 2014 to 2021). A usually aggressive malignant bone-forming mesenchymal neoplasm, predominantly affecting adolescents and young adults. "BTG2 can also inhibit osteosarcoma cell multiplication and metastasis via restraining PI3K/AKT pathway." (PMID 34082648, 2021).
pancreatic ductal adenocarcinoma (4 papers, 2018 to 2024). An infiltrating adenocarcinoma that arises from the epithelial cells of the pancreas. "miR-365 secreted from M2 Macrophage-derived extracellular vesicles promotes pancreatic ductal adenocarcinoma progression through the BTG2/FAK/AKT axis." (PMID 38396328, 2024). "In addition, M2 macrophages in the TME secrete miR-365 through extracellular vesicles, thus promoting pancreatic ductal adenocarcinoma progression through activation of the BTG2/FAK/AKT axis." (PMID 39152432, 2024).
Anxiety (3 papers, 2012 to 2022). Intense feelings of nervousness, tension, or panic often arise in response to interpersonal stresses. "Thus, further studies are required to identify the developmental age showing the crucial alteration in the induction of the Btg2 and Adamsts1 genes as well as behavioral alterations associated with anxiety after treatment with the anxiogenic drug." (PMID 22913326, 2012). "The present study suggests a functional coupling between the GABAergic system and the transcriptional regulation of the two genes (Btg2 and Adamsts1) in the hippocampus of adult mice, which may play a role in the brain function related to anxiety and stress such as memory of fear." (PMID 22913326, 2012).
brain tumor (3 papers, 2016 to 2025). "On the molecular level, all three cell cycle arrest genes that were upregulated under combination therapy in our study (GADD45A, CDKN1A, and BTG2), where Cx43 function was inhibited, showed a positive correlation with GJA1 levels in brain tumor tissue." (PMID 39680504, 2025). "Our DNA microarray analyses have identified several tumour suppressors as candidate downstream targets of TLX and TET3, including BTG2 and PPP2R1B, which were also upregulated upon TLX knockdown in PBT003-grafted brain tumours in NSG mice." (PMID 26838672, 2016).
breast tumor (3 papers, 2016 to 2019). "One of these downregulated genes is BTG2 (B- cell translocation gene-2), which has antiproliferative activity and has been reported to be altered in breast tumours." (PMID 30961553, 2019).